NOTCH1 (notch receptor 1)
Diseases named in the same sentence as NOTCH1 in open-access papers (continued):
Sharing a sentence is not in itself a finding about the gene and the disease.
tumor (continued). "Here we investigate a new role of Notch1 in genomic instability and demonstrate that blockade of both Notch1 and the DNA repair factor ChK1 causes extensive DNA damage and tumor cell death increasing survival in MBM bearing mice." (PMID 40437523, 2025). "Though our patient’s tumor lacks NOTCH1 mutations, it is unclear if this is linked to his response to vorasidenib." (PMID 39857783, 2025). "Consistent with this, P.g. has been linked to chemoresistance in OSCC cells via Notch1 activation, suggesting a mechanism that enables tumor growth despite treatment." (PMID 40924302, 2025). "Significant associations were observed between high Notch1 expression and high-grade tumors (P=0.029), deeper tumor invasion (P=0.01), lymph node involvement (P=0.011), and advanced tumor stage (P=0.012)." (PMID 40060224, 2025). "In the context of CRC, deletion of a single JAG1 allele in an APC mutant background significantly reduces tumor burden, which is associated with decreased levels of active Notch1." (PMID 41294868, 2025). "A genomic analysis of the Notch pathway in 16 glioma tumor-initiating cell populations identified genes such as NOTCH1, NOTCH3, MAML1, JAG2, HES1, and DLL-3, which were associated with active Notch signaling and enriched in tumors responsive to treatment." (PMID 40003637, 2025). "Notch1 blockade can interfere with tumor vessel function but causes tissue hypoxia and gastrointestinal toxicity." (PMID 38984877, 2024). "Macrophages also express the Notch1 ligand Jagged1, which engages the Notch1 receptor on tumor cells, causing nuclear translocation of the Notch1 intracellular domain (NICD)." (PMID 39555068, 2024). "In head and neck tumours, Mutations in NOTCH-1 indicate a function as a tumour suppressor, while activation of the NOTCH signalling pathway suggests a proto-oncogenic effect." (PMID 39046819, 2024). "The structural characterization of NOTCH1 mutations in HNSCC demonstrates that most are predicted to cause loss of function, in agreement with NOTCH1’s role as a tumor suppressor in this cancer." (PMID 38540309, 2024). "Since gain-of-function mutations in NOTCH1 can transform normal cells into tumor cells in many different cell types, we rationalized our analysis to focus on common NOTCH1 interactors between cell types." (PMID 38043798, 2024). "Most NOTCH1 mutations in patient samples are considered inactivating, indicating that NOTCH1 is a tumour suppressor gene." (PMID 38926351, 2024). "Sustained activation of Notch1 signaling in tumor-associated ECs induces VCAM1 expression, neutrophil recruitment and a senescent, pro-inflammatory endothelium which promotes tumor cell adhesion, intravasation and metastasis." (PMID 38426109, 2024). "NOTCH1, a gene associated with tumor metastasis, has been reported to be differentially expressed between tumor border cells and tumor core cells." (PMID 39430248, 2024). "In the mouse oesophagus, NOTCH1 wild-type cells are more likely to contribute to tumours than NOTCH1 mutant cells; NOTCH1 loss reduced tumour size by slowing cell division and attenuating signalling downstream of mutant ATP2A2." (PMID 38172609, 2024). "Patient 29 acquired a Notch1:p.F937L mutation that was accompanied by a transformation in IDH mutation status during tumor evolution." (PMID 37533228, 2023). "IL-17, for example, is linked to NSCLC tumor progression via STAT3/NF-κB/Notch1 signaling in Th17 cells, and inhibition of the pathway was found to slow metastases." (PMID 35881197, 2023). "To understand how Notch1 loss alters tumor growth, we sequenced tumors from Notch1−/− epithelium, finding they share the same driver mutation, Atp2a2, (6/7 tumors), as the tumors from Notch1+/+ epithelium (17/17 tumors) 35,36." (PMID 36658434, 2023).
tumor (continued). "We conclude that Notch1 mutations in normal epithelium are beneficial as wild-type Notch1 favors tumor expansion." (PMID 36658434, 2023). "Significant multiplicative-scale interaction between Tumor differentiation and the presence of NOTCH1 on mortality risk was identified (P=0.0081)." (PMID 37859809, 2023). "The loss of Notch1 or Notch2 in melanocytes appeared to accelerate tumor formation and growth in BP mice, and lead to shorter survival compared to control mice." (PMID 36672468, 2023). "In carcinogenesis models, NOTCH1 mutations are less frequent in tumors than in normal esophageal epitheliums; furthermore, NOTCH1 deletion reduces tumor growth, as well as the pharmacologic inhibitors of NOTCH1." (PMID 36661697, 2023). "Activating and oncogenic GoF mutations in the NOTCH receptors (mostly NOTCH1) typically play a role in promoting later-stage tumor progression but can also act as gatekeepers or lineage-specific driver mutations involved in cancer initiation, such as in T-ALL." (PMID 37760535, 2023). "The positive Notch 1 expression was significantly associated with poor tumor differentiation status." (PMID 37859809, 2023). "For example, while NOTCH1 mutations are a strong driver of clonal expansion in normal esophagus, these same mutations also impair tumor growth in mice models." (PMID 37890493, 2023). "In contrast, it is known that HES1 mediates the tumor-suppressive roles of NOTCH1 signaling in AML development as well, which underlines the context-dependent manner of NOTCH1 signaling." (PMID 37833915, 2023). "Out of these risk factors studied, increasing age, postmenopausal status, bilaterality, complex tumour morphology and increased Notch1 score were associated with a higher risk of malignancy." (PMID 37489207, 2023). "In LSCC, NOTCH1 acts as a tumor suppressor gene, and most of the mutations are loss-of-function mutations of the epidermal growth factor (EGF)-like ligand or the NOTCH intracellular domain (NICD)." (PMID 37629093, 2023). "Notch1 mutations have opposing effects on clonal growth in normal and tumor cells of the mouse esophagus." (PMID 36658434, 2023). "Notch1 illustrates how inactivating mutations in the same gene can drive clonal expansion in normal tissue but impair tumor growth." (PMID 36658434, 2023). "In another xenograft model, NOTCH1 inhibition was shown to cause a reduction in cell growth, increased cell death, and delayed tumor growth." (PMID 36672468, 2023). "NOTCH1-mutated tumours did show higher expression of serine/glycine metabolism enzymes PHGDH, SHMT1 and SHMT2." (PMID 36932191, 2023). "NOTCH1 was found to be the second most frequently mutated gene in the genomes of HNSCCs, suggesting that it functions as a tumor suppressor gene with a prevalence rate of 15%–19%." (PMID 37205904, 2023). "It is possible that driver events in these four tumours are point mutations in NOTCH1 or in other genes that dysregulate NOTCH1 signalling, which we cannot unequivocally assess in bulk transcriptomes." (PMID 37749094, 2023). "Studies realized in GBM uncovered that the tumor-suppressive feature of EA was linked to the inactivation of the Akt and NOTCH1 signaling pathways whose controlling genes are upregulated in MB." (PMID 36677837, 2023). "The NOTCH1 c.6208C > T mutation, detected only in tumor DNA by NGS was validated in tumor and plasma samples with an allele frequency of mutant copies of 7.7% and 1.7%, respectively (Patient No. 3)." (PMID 36420687, 2023). "NOTCH3 is associated with tumor staging, lymph node and distant metastasis in this subtype, whereas NOTCH1-signaling correlates with poor prognosis and drives metastasis." (PMID 37860822, 2023).
tumor (continued). "Positive association has been shown between the Notch receptor, Notch1, expression and deeper invasion of tumor-lymph node-metastasis (TNM) in CRC." (PMID 36229883, 2022). "Next, we analysed the expression of Usp28 and its substrates c‐Myc, c‐Jun and Notch1 at various grades in murine primary tumours, generated by intratracheal infection with a KP encoding AAV." (PMID 35364627, 2022). "The association between NOTCH1 signaling in tumor cells and the state of the surrounding immune microenvironment has not been examined so far in HNSCC." (PMID 35205828, 2022). "NOTCH1 likely plays a bimodal role in HNSCCs, with inactivating mutations indicating a tumor suppressor role and activating mutations and upregulation consistent with an oncogenic role." (PMID 36359251, 2022). "The upregulated Notch1 signalling pathway was linked to metastasis, increased tumour size, and led to a poor prognosis in PTC patients." (PMID 36686473, 2022). "Tumors with NOTCH1 mutations represent a distinct tumor phenotype with increased activation in Notch1 signaling." (PMID 36226253, 2022). "Nevertheless, they were classified as likely pathogenic because NOTCH1 is also described as a tumor suppressor." (PMID 36077692, 2022). "The identification of genomic alterations in HNSCC has yet to improve patient outcomes because most alterations are in tumor suppressors, including NOTCH1, which is mutated in ~20% of patients." (PMID 36124629, 2022). "Recently, the downregulation of the NOTCH1 signaling pathway has been associated with decreased vessel co-option and reduced perivascular tumor cell population." (PMID 36294763, 2022). "Another potential mutation that also alters the tumor microenvironment is loss or mutation of the NOTCH1 oncogene, which is mutated in 19% of head and neck cancers and regulates macrophage recruitment and M1/M2 macrophage polarization." (PMID 35154165, 2022). "Prolonged Notch1 activation in the epithelial cells cause a senescence-like state, allowing tumor cells to trans-migrate from the main tumor and recruitment to distant locations." (PMID 36229883, 2022). "This pattern of Notch1 positive CD8+ T-cells associated with increased anti-tumor effect, as ZM treatment significantly suppressed tumor organoid growth and increased cancer cell death compared to control and CGS-treated organoids." (PMID 36090975, 2022). "Notch1 loss induces the expression of matrix metalloproteinases, cytokines and chemokines to alter the tumor microenvironment." (PMID 35154165, 2022). "Other studies reported NOTCH1 mutations in 15–26% of HNSCCs, suggesting that NOTCH1 acts as a tumor suppressor in HNSCC." (PMID 36359251, 2022). "Organoid histology and NICD1 expression were similar to those seen in the parental tumor and persistence of both NOTCH1 mutations in the organoid model was confirmed by WES." (PMID 35931701, 2022). "At the same time, NOTCH1 is reported to be overexpressed in a variety of tumors and associated with advanced tumor stages." (PMID 35205828, 2022).
tumor (continued). "The authors concluded that Dll4 is associated with gastric cancer progenitor cells, and its expression influences features linked to the Notch-1 pathway involving tumor formation, growth and development." (PMID 35406423, 2022). "Dysregulation of the Notch1 pathway has been linked to the development and progression of a variety of human neoplasms." (PMID 36297616, 2022). "In the same tumor context, a Chinese study described a positive Notch1 association with the expression of the melanoma cell adhesion molecule (MCAM), an EMT activator protein." (PMID 35582386, 2021). "Mutations in NOTCH1 inhibit the differentiation of Th2 cells, facilitating tumor progression through a decrease in Th2 cell recruitment and differentiation." (PMID 34391381, 2021). "Using computational prediction, we identified NF1 p.T700I and NOTCH1 p.V2153M as tumor-associated neoantigens, representing potential therapeutic targets for immunotherapy." (PMID 34503126, 2021). "In contrast, tumour-promoting NOTCH1 mutations have been frequently identified in the Chinese population, for example in oesophageal squamous cell carcinoma." (PMID 34944837, 2021). "The variants observed in NOTCH1, 2 and 3 illustrates this point: 11/27 (41%) cases showed alterations in one of these genes analyzing only the tumor DNA, however, only in three cases the variants appeared to be somatic when comparing tumor with germline DNA." (PMID 33500480, 2021). "The enrichment of tumor cells in the bronchiolar lumen is reasoned by Notch1 deficiency on lateral inhibition in the tumor cells." (PMID 34257546, 2021). "Notch1 has been more extensively studied, showing an important role in tumour metastasis when expressed in tumour‐associated endothelial cells." (PMID 33955149, 2021). "ACC is commonly associated with truncation of MYB and elevated NOTCH1 expression/activity, and this patient's tumor presented with both." (PMID 33733072, 2021). "On the other hand, Notch1 plays a key role in the loss of epithelial characteristics and the concomitant acquisition of mesenchymal traits and invasive potential of tumor cells." (PMID 33922104, 2021). "Triple negative subtype and low CD34 MVD positivity in Notch 1 hotspots showed significant association with tumor recurrence." (PMID 34642389, 2021). "These biomarkers include a serum miRNA profile, SNPs in genes associated with an anti-angiogenic response, and Notch 1 expression in diagnostic primary tumor biopsies." (PMID 33916610, 2021). "The reason for allele specificity with respect to Notch1 tumor suppressor gene function in this context is unclear." (PMID 34475389, 2021). "Consistent with its tumor-suppressive role, mutations in NOTCH1-4 were significantly associated with a poorer prognosis in the combined cohort (HR 1.67, 95% CI 1.01–2.69, P = 0.046)." (PMID 34145257, 2021). "Genome sequencing of HNSCC suggested NOTCH1 acts as a tumour suppressor gene, and was the second most frequently mutated with an incidence of 15–19%." (PMID 34298667, 2021). "Tumor DNA analysis revealed a p.Q1978* mutation in NOTCH1 gene that introduces a premature stop codon, resulting in a truncated protein." (PMID 33466719, 2021). "In this regard, SCCE harbored recurrent NOTCH1 mutations, contributing to the formation of an immune-suppressive tumor microenvironment (TME) and exhibiting great potential in the development of antitumor immunotherapies." (PMID 33980813, 2021). "It was reported that tumor-infiltrating macrophages (TIMs) are involved in microenvironmental interactions in NOTCH1-mutated patients." (PMID 34956871, 2021).
tumor (continued). "Notch1 expression was increased in HCC and tumor metastasis (TNM) stage was significantly associated with increased Notch1 mRNA levels." (PMID 34988028, 2021). "We have linked Lama3 mutations to tumour invasiveness and Notch1 mutations to an increased immune cell infiltrate, and explored the clonal architecture of individual tumours." (PMID 33168804, 2020). "Given our finding that NOTCH1 promotes BRCA1-deficient tumour growth by activating ATR–CHK1 and inducing EMT, we inhibited the ATR/CHK1 pathway in combination with a low dose of cisplatin to effectively kill TNBC in our mouse model and PDX model." (PMID 32591500, 2020). "Alternations of NOTCH1 signaling have been implicated in stress responses and can be tumor-suppressive or tumor-promoting." (PMID 32331221, 2020). "Laminin-α3 mutations are associated with tumour invasiveness and Notch1 mutant tumours have an increased immune infiltrate." (PMID 33168804, 2020). "The only statistically significant association found was between NOTCH1 mutation and tumor size: all tumors with NOTCH1 mutation (11/11; p = 0.023) had a higher T-stage (T3/T4)." (PMID 32561788, 2020). "Notch1 was found to be upregulated in glioma tissues and cell lines, and positively associated with increasing tumor grade." (PMID 35582224, 2020). "Analysis of protein levels in BRCA1-deficient tumours indicated that a high protein expression level of NOTCH1 correlated with TNBC incidence." (PMID 32591500, 2020). "A challenge to developing targeted therapy for HNSCC is the dominance of mutations in tumor suppressors including NOTCH1, which is mutated in about 17% of HPV-negative HNSCC." (PMID 33322834, 2020). "In nude mice bearing PC-3 PCSC-derived tumors, the combination of GSI and DOX reduced the tumor growth, which was associated with the decreased Notch-1 expression in tumor tissues." (PMID 32586404, 2020). "In LADC, a hypoxic tumor microenvironment can potentially cause the dysregulation of NOTCH1 and ITGA4 signaling pathways." (PMID 31217907, 2019). "Lastly, tumor growth in mice transplanted with T-ALL DECRREE2 (HD-domain mutation) was completely inhibited by the treatment with the NRR-targeting anti-Notch1 mAb, but unaffected by Dll4 ligand blockade." (PMID 31399482, 2019). "Loss of Notch1 promotes a tumor-inducing effect, impairing barrier integrity and generating a wound-like environment in the underlying stroma." (PMID 30917608, 2019). "NOTCH1 exhibited mutational changes in 70 % plasmas, much higher than in tumor tissue (20%), highlighting the extraordinary usefulness of NOTCH1 in liquid biopsy." (PMID 31369215, 2019). "A high level of Notch1, Notch3, and Notch4 expression is associated with poor clinical outcomes of BC, in contrast to Notch2, which was recognized as a neoplasm suppressor." (PMID 31357442, 2019). "By contrast, 4 clusters of clones were identified in the recurrent tumor tissues and the clone 3 still existed with additional NOTCH1 mutation." (PMID 30850667, 2019). "To examine the effects of mutations on NOTCH1 expression, we performed real-time PCR of mRNA extracted from cell lines, and immunostaining for NOTCH1 in sections of the original tumours." (PMID 31827722, 2019). "This approach greatly differs from ours, where we traced Notch1+ cells in spontaneously arising tumours generated by somatic loss of heterozygosis (LOH) at the Apc locus or by a carcinogenic agent." (PMID 30696875, 2019).